LAG3 (lymphocyte activating 3)
Diseases named in the same sentence as LAG3 in open-access papers (continued):
Sharing a sentence is not in itself a finding about the gene and the disease.
tumor (continued). "Firstly, there is a need to explore the most selective and active cMET inhibitor with less off-target toxicities and high anti-tumor activity and then to evaluate the best ICI agent (anti-PD1 or/and anti-LAG3) to combine for mUM treatment." (PMID 36761417, 2022). "As a novel functional ligand of lymphocyte-activation gene 3 (LAG3), FGL1 can promote the proliferation of tumor cells." (PMID 34975333, 2022). "There is also the expression and interaction of immune checkpoint molecules between tumor cells and immune cells to protect cancer cells from the attack of immune cells, such as PD-1, PD-L1, CTLA-4, LAG-3, ID-1 and tim-3." (PMID 35892755, 2022). "High-dose crizotinib induces immunogenicity in tumor cells and increases the expression of PD1, LAG3, and PDL1, in a mouse model for lung cancer, therefore preparing the tumors for immunotherapy with anti-PD1 antibodies." (PMID 36761417, 2022). "It is worth noting that when the interaction between LAG3 and ligand FGL1 is blocked by monoclonal antibodies, the T cell response in the tumor is enhanced and the tumor volume decreases, which provides a new idea for targeted immunotherapy." (PMID 35590394, 2022). "Tumors with alterations in only BAP1 showed a distinct pattern of expression of inflammatory tumor microenvironment genes, including activation of interferon signaling and IRF TFs and high LAG3 and VISTA expression." (PMID 36428720, 2022). "For instance, humanized monoclonal antibodies that are specific for inhibitory receptors (such as CTLA-4, PD-1, LAG-3, and TIM-3) and ligands (PD-L1) expressed on T lymphocytes, antigen-presenting cells, and tumor cells." (PMID 36298592, 2022). "The general perception is that IC molecules, such as PD1, CTLA4, LAG3, and TIGIT, are expressed in T cells and NK cells, and the ligands are expressed in the other cells, including tumor cells and myeloid cells." (PMID 36211375, 2022). "The chronic inflammation induces immune exhaustion and dysfunction by firmly braking the immune activation signals via inducing expression of multiple IC molecules, including CTLA4, PD1, TIM3, LAG3, and TIGIT, in anti-tumor effector cells." (PMID 36211375, 2022). "PDCD1, CD274, CTLA4, LAG3, TIGIT, and HAVCR2 are important immune checkpoints responsible for tumor immune escape." (PMID 35252356, 2022). "At present, immune checkpoints including PD-L1, CTLA-4, LAG3, TIGIT and TIM-3, are thought to contribute to tumor immune escape." (PMID 35665772, 2022). "After MWA, the expression of LAG3 was up-regulated on sub-populations of TILs, and introducing LAG3 blockade to MWA postponed tumor development and extended survival in the MC38 tumor model." (PMID 36180876, 2022). "Specifically, activated Treg cells destroy tumour immunity by enriching a series of costimulatory molecules (such as ICOS, CD27, 41BB, OX40, and GITR) and immune checkpoints (PD-1, CTLA-4, LAG3, and TIGIT) to promote tumour immune evasion." (PMID 36110969, 2022). "Among them, Lymphocyte-activation gene 3 (LAG-3) is one of the important immune checkpoint molecules and has been clinically demonstrated to have synergistic anti-tumor effects in combination with PD-1 antibody." (PMID 36518768, 2022). "More specifically, anti-LAG3 and GSK-3 inhibitor SB415286 decreased tumor growth and prevented lung metastasis in a murine melanoma model." (PMID 35911672, 2022). "CTLA4, HAVCR2, PVRL2, PDCD1, SIGLEC15, TIGIT, and VTCN1 expression levels were higher in tumor tissues, while CD244, LAG3, PDCD1LG2, and CD274 expression levels were found to be lower." (PMID 35923695, 2022). "SIGLEC15, PDCD1LG2(PD-L2), TIGIT, PDCD1(PD-1), CD274(PD-L1), CTLA4, LAG3, and HAVCR2(TIM3) are immunological checkpoints that perform a vital function in tumor immune evasion." (PMID 35840882, 2022). "It has become apparent that multiple axes of immune suppression restrain the capacity of T cells to provide anti-tumour activity including signalling through PD1/PD-L1 and LAG3/MHC-II." (PMID 34969998, 2022).
tumor (continued). "Intriguingly, in this study following recovery of the tumour cells post-FLOT treatment TIM-3, LAG-3 and A2aR expression on the surface of OE33 cells was significantly decreased compared with the vehicle control." (PMID 35228614, 2022). "Tumor cell-extrinsic mechanisms encompass increased recruitment and activity of inhibitory immune cells within the TME and upregulation of LAG-3 and TIM-3." (PMID 36613491, 2022). "Blocking the interaction between LAG-3 and FGL1 with a monoclonal antibody increases intertumoral T cell responses and leads to decreased tumor size in murine models of melanoma." (PMID 35885017, 2022). "In primary tumors with LA, LAG3 was directly correlated with PD-L1 expression (r=1, p<0.001) and the only 2 cases with LAG-3 positive tumor cells had LA." (PMID 36313661, 2022). "The analysis of immune checkpoint molecules from stromal cancers found PD1, lymphocyte activation gene 3 (LAG3), and T-cell immunoglobulin mucin 3 (TIM3) upregulation on tumor-infiltrating T-cells compared matched control blood cells." (PMID 35242139, 2022). "Studies have shown that the combination of LAG-3 and MHC-II contributes to avoiding apoptosis of tumour cells and promoting tumour-specific CD4+ T-cell recruitment but reduces the response of CD8+ T cells." (PMID 35494015, 2022). "The effectiveness of anti-PD-1 therapy was shown in a study with tumor-infiltrating CD8 with high PD-1 expression treated with anti-PD-1 and anti-TIM3 and/or LAG3 therapy had restored hindered proliferation and cytokine production." (PMID 34689234, 2022). "In a cohort of 47 resected HCC studied for leukocytes infiltration in the tumoral (TILs) and tumor-free regions, TIGIT was enriched in PD1highCD8+ TILs and it was co-expressed with LAG3 and TIM3 exhaustion markers." (PMID 36230819, 2022). "These humanized monoclonal antibodies target inhibitory receptors (CTLA-4, PD-1, LAG-3, TIM-3) and ligands (PD-L1) expressed on T lymphocytes, antigen-presenting cells, and tumor cells, eliciting an anti-tumor response by stimulating the immune system." (PMID 35269781, 2022). "Previous studies have shown that infiltration of multiple immune cells, activation of CD274 (PD-L1), LAG3 and HAVCR2(TIM-3) and high immune scores played a crucial role in hot tumor." (PMID 35860239, 2022). "Tumor ROIs of short-term survivors revealed a high expression of molecules correlated with immune suppression such as PD-1, PD-L1, CTLA4, LAG3, FoxP3, and CD25 compared to long-term survivors." (PMID 36685537, 2022). "Meanwhile, in the MC38 tumor model, introducing LAG3 blockade to MWA extended survival and postponed tumor development." (PMID 36180876, 2022). "Conversely, dual blockade of the LAG-3 and CTLA-4 pathways using PD-1 knockout mice led to tumor-free survival in 40% of treated mice." (PMID 36077354, 2022). "Some of these biomarkers are immunosuppressive or have pro-tumor activity such as PD-L1, IL17RE, LAG-3, IDO-1, TIM-3 whereas others have antitumor activity such as CD8+ T-cells, OX40, CXCL9 and others have a mixed role such as IFN-G." (PMID 36612271, 2022). "Co-expression of LAG-3 and PD-1 on TILs in the TME gives rise to T cell exhaustion and the consequent unlimited tumor growth." (PMID 35967381, 2022). "The immune-checkpoint genes PD-L1 (CD247), CTLA4, LAG3, TIM3 (HAVCR2) and IDO1 were assessed using gene expression data, with significantly higher expression of each in DDIR-positive tumours." (PMID 34728791, 2022). "Unexpectedly, a high level of SPINK1 expression was found to be significantly and positively correlated with the high expressions of PD-1, LAG-3, TIM-3, TIGIT, and CTLA-4 in the tumor samples from the TCGA cohort." (PMID 35924241, 2022). "SIGLEC15, PDCD1LG2 (PD-L2), TIGIT, PDCD1 (PD-1), CD274 (PD-L1), CTLA4, LAG3, and HAVCR2 (TIM3) are transcripts related to immunological checkpoints that perform a vital function in tumor immune evasion." (PMID 36042287, 2022).
tumor (continued). "More CD4+ and CD8+ T cells accumulated in tumour tissues, and CD8+ T cells had lower expression of checkpoint molecules such as lymphocyte activation gene 3 protein (LAG‐3) and programmed cell death protein 1 (PD‐1)." (PMID 35665592, 2022). "CD8+ T lymphocytes are the primary cytotoxic tumor-infiltrating lymphocyte subset in HCC, and the immune checkpoints PD-1, CTLA-4, and LAG-3 are negative regulators of CTL function." (PMID 35912257, 2022). "High LAG-3 and FGL1 expression boosts tumor growth by inhibiting the immune microenvironment, essentially helping the tumor cells to evade autoimmune elimination." (PMID 35885017, 2022). "SIGLEC15, PDCD1LG2(PD-L2), TIGIT, PDCD1(PD-1), CD274(PD-L1), CTLA4, LAG3, and HAVCR2(TIM3) are transcripts related to immunological checkpoints that perform vital functions in tumor immune evasion." (PMID 36253777, 2022). "We observed significantly higher levels of exhaustion (ICOS, TIM3, CTLA4, PD1, LAG3, TIGIT) and activation (TNFSR9, CD69, CD25) markers for clonotypes restricted to the tumor." (PMID 36185254, 2022). "In summary, inhibitory ICs TIM-3, LAG-3, CTLA-4 and PD-L2 and stimulatory IC ICOS were significantly upregulated on tumour-infiltrating T cells compared with peripheral circulating T cells in OAC patients." (PMID 35366537, 2022). "Nearly all available tumor samples were of clear cell histology, and among clear cell RCC cases, LAG3 levels were significantly lower in metastases." (PMID 36313654, 2022). "Tumour infiltration of CD8+ T cells was also enhanced by napabucasin treatment, and exhibited lower levels of LAG‐3, PD‐1 and high levels of Granzyme B, Perforin, IFNγ in the napabucasin‐treated mice than in the control group." (PMID 35665592, 2022). "Lymphocyte activation gene 3 (LAG3), also known as CD223, is an immune checkpoint receptor highly expressed on activated regulatory CD4 and CD8 T-cells, tumor infiltrating lymphocytes, B-cells, natural killer cells, and dendritic cells." (PMID 35954384, 2022). "The data revealed that the exhaustion status of CD8+ T cells was significantly improved in MPR tumor lesions, with reduced expression of exhausted markers, such as PDCD1, CTLA4, LAG3, and TIGIT." (PMID 35831283, 2022). "Chronic antigen stimulation is known to produce up-regulation of PD-L1/PDL-2 on tumor cells and expression of exhaustion markers, such as PD-1, TIM-3, LAG-3, and TIGIT on T-lymphocytes, which hamper immune response." (PMID 35740552, 2022). "Relatlimab (BMS-986016) is a monoclonal antibody that blocks the interaction of LAG-3 and MHC-II in tumor cells." (PMID 36140182, 2022). "Other predictive biomarkers of response are PDL-1 expression, LAG-3 expression, CD8+ T cells at tumor invasive margin, IL-17 expression, immune-related gene expression signatures, and T-cell receptor (TCR) signature." (PMID 36613491, 2022). "In TME, certain tumor ligands bind to inhibitory molecules on T cells, such as CTLA-4, PD-1, TIM-3, and LAG-3 and others, which in turn produce immune-suppressive mediators, leading to the failure of cancer elimination." (PMID 35655158, 2022). "LAG3 (or CD223), like PD-1, is expressed on a variety of cell types, such as tumor-infiltrating lymphocytes (CD4, CD8) and regulatory T cells." (PMID 36551617, 2022). "LAG3 is expressed on regulatory T cells in tumors and induces the production of IL-10 and TGF-β1, which helps tumor immune escape." (PMID 35279104, 2022). "The CD8+ T cells, the inflammation-promoting function, the high immunity score, the activation of CD27, LAG3, and TNFRSF18, played a critical role in the hot tumour." (PMID 35937987, 2022). "Our results showed that the high-risk group with poor survival had a higher expression of T cell exhaustion markers, such as PDCD1/PD1, CTLA4, TIM3, LAG3, VSIR and TIGIT, which lead to tumor immune evasion." (PMID 36147509, 2022). "LAG3 can bind to its ligands, such as MHC II expressed on tumor cells or antigen presenting cells, to transmit inhibitory signals." (PMID 35894707, 2022).
tumor (continued). "Through immune checkpoint gene expression analysis, the expression of HM13 was found to exhibit a significant correlation with several tumor inhibitory genes, especially VEGFB, LAG3, CD274, and TGFB1." (PMID 36046831, 2022). "These mAbs block the interaction between LAG-3 and MHC-II in the TME and improve the induction of apoptosis in the tumor cells." (PMID 35967381, 2022). "For example, LAG-3-Ig fusion proteins like IMP321 or eftilagimod alpha increase the expression of co-stimulatory molecules and IL-12 secretion that, finally enhances tumor immunity." (PMID 35967381, 2022). "CD39 is a marker of exhausted tumor-infiltrating CD8 + T cells and co-expresses with multiple inhibitory receptors, such as PD-1, LAG-3, and Tim-3." (PMID 36316782, 2022). "Each CD44+ cell-type functions immunosuppression through different ways: CD44+ tumor cells express CD276, IL13, VEGFA, and IDO1; CD44+ TAMs express IL10, TGFB1, VEGFA, and HAVCR2; CD44+ T cells express CD274, TGFB1, CTLA4, LAG3, and PDCD1." (PMID 35187044, 2021). "More than 90 % of tumor-infiltrating host CD8+ TEM cells expressed PD-1, while approximately 60 % expressed LAG-3 and/or TIM3." (PMID 34625113, 2021). "Checkpoint proteins such as CTLA-4, PD-1, LAG-3, TIM-3, VISTA and TIGIT are mostly found on the surface of T-cells, with some also found on dendritic cells (DCs) and monocyte/macrophages (PD-L1, TIM-3, LAG-3, VISTA) or tumour cells (PD-L1, TIM-3)." (PMID 33923305, 2021). "HLA class II (ligand for LAG3), PD-L1 (ligand for PD-1), HLA-E (ligand for NKG2A), and CEACAM1 (ligand for TIM3) were all expressed on tumor organoids, suggesting that the opT cells were likely to be regulated by these checkpoint proteins." (PMID 34789550, 2021). "Further phenotypic dissection of the CD8+TILs from mouse tumor models reveals that an exhausted phenotype is presented with an increased expression of TIGIT, PD-1, Tim-3, Lag-3, CD101, CD38, and eomesodermin (Eomes) in CD226loCD8+TILs." (PMID 33670993, 2021). "LAG-3:MHC class II binding contributes to tumor escape from apoptosis and facilitates recruitment of tumor-specific CD4 T cells, but with a reduction of the CD8 T cell response." (PMID 34067904, 2021). "In the LAG-3+ subgroup, TIL PD-L1 expression was also dramatically higher than tumor PD-L1 expression." (PMID 33717059, 2021). "At days 11 and 14, CD4+ and CD8+ tumor-infiltrating lymphocytes (TILs) were analyzed for Nr4a3-Timer, PD1, Lag3, and Ifng-YFP expression." (PMID 34534438, 2021). "Besides, aberrant amplification or deletion event associated with immune checkpoint stimulator genes (CD247, CD274, PD-1, PD-L1, and LAG3) was observed in distinct subgroups, upregulation of which expression could restrict anti-tumor response and facilitate immune escapes." (PMID 33407498, 2021). "Despite being traditionally considered as exhaustion T-cell markers, PD-1, LAG-3 and TIM-3 are expressed preferentially in activated tumor infiltrating lymphocytes (TILs)." (PMID 34923982, 2021). "On the other hand, NK DNAM-1+ cells expressed more CD16, an antigen-dependent cytotoxicity receptor with anti-tumor effect in HCC, and less LAG-3 and CD39." (PMID 33498698, 2021). "In these immunosuppressive marker genes, TGFB1, NECTIN2, LGALS9, LAG3, and IL10RB were significantly correlated with CCDC137 expression in most tumor types." (PMID 34055889, 2021). "Ligands for LAG-3 include MHC-II, Galectin-3 (Gal-3), and liver sinusoidal endothelial cell lectin (LSECtin) expressed by certain tumor types." (PMID 33804419, 2021). "The combination of IL-10 and IL-35 secreted by tumor-infiltrating regulatory T cells was shown to induce the expression of the inhibitory receptors TIM-3, LAG-3, TIGIT, and 2B4, driving intratumoral CD8+ T cells to exhaustion." (PMID 33679743, 2021). "Relative to other tumor-infiltrating T cells, CD103+ TRM also displayed upregulation of immune checkpoint receptors such as PD-1, LAG-3, CTLA-4 and TIM-3." (PMID 34571883, 2021).
tumor (continued). "To verify our guess, we investigated tumor-related immune checkpoints, including CD273, CD274, CTLA-4, and the ones that were newly emerging, LAG-3, TIM-3, TIGIT, CD276, BTLA, and IDO1, between the two subgroups." (PMID 33558879, 2021). "While anti-LAG-3 therapies have shown preclinical success, LAG-3 is expressed in a small percentage of tumor-infiltrating lymphocytes, thus limiting the potential impact of these therapies on stimulating the immune response." (PMID 34298615, 2021). "Interaction between LAG-3 and Galectin-3, a soluble lectin regulating antigen-specific T-cell activation, expands the immunomodulatory effect of LAG-3 on tumor-infiltrating CD8+ T-cells in the TME." (PMID 33562324, 2021). "Previous studies showed that anti-LAG-3 antibodies increased CD8+ T cell effector capabilities and decreased tumor growth in vivo." (PMID 33670942, 2021). "Novel therapies targeting inhibitory (e.g., IDO-1, LAG-3, TIGIT, TIM-3, VISTA) and stimulatory (e.g., ICOS, GITR, OX40, 4-IBB) proteins within the tumor microenvironment (TME) are under active investigation." (PMID 34093591, 2021). "This combination regimen results in decreased levels of myeloid-derived suppressor cells (MDSC), splenic and intratumoral checkpoint-expressing T cells (PD-L1, LAG-3 and CTLA-4) and therefore positively modulates the tumor microenvironment." (PMID 33870463, 2021). "Anti-LAG-3 or anti-FGL1 antibody treatment allows T cells to be reactivated, leading to a decrease in tumor size." (PMID 34572799, 2021). "Overexpression of CTLA4 and TIM3 in Treg cells and overexpression of LAG3 and TIM3 in tumor infiltrating T lymphocytes can prevent the activation of effector T cells, also resulting in immune escape of tumor cells." (PMID 34975896, 2021). "Treg cells are involved in tumor progression by explicitly improving the expression of CTLA4; glucocorticoid-induced TNF receptor (GITR); IL-2, IL-10 and IL-35; lymphocyte-activation gene-3 (LAG3); and TGF-β." (PMID 34834282, 2021). "In patients with NSCLC PD-1, TIM-3, CTLA-4, LAG-3, and BTLA inhibitory receptors were detected on TILs with a gradual and continuous upregulation during tumor progression, in 24 tumor lesions." (PMID 35069581, 2021). "Nevertheless, the proper correlation of LAG-3 single-domain antibody uptake levels with flow cytometry data could have been clarified by also analyzing tumors using immunohistochemistry, as it would have allowed us to more accurately quantify the percentage of immune cells per unit weight of tumor." (PMID 33712537, 2021). "We found that the exhausted CD8+ T cells located in the core of the tumor had a higher expression of immune checkpoint molecules, including PDCD1, CTLA4, LAG3, TNFRSF9/CD137, CD27, and HAVCR2." (PMID 34513820, 2021). "Activation of LAG-3 can elevate intratumoral Tregs activity, and blocking of it will upregulate T-cell function and reinvigorate CD8+ tumor-infiltrating lymphocytes (TILs) to eliminate tumor cells." (PMID 34917131, 2021). "Further, activated CAR-T cells mainly express immune checkpoint molecules, including CTLA4, PD1, LAG3, abrogating CAR-T anti-tumor activity." (PMID 34321099, 2021). "The tumor extrinsic mechanisms of AR are mainly through the upregulation of other immune checkpoints, such as TIM-3, LAG-3, and VISTA." (PMID 34194441, 2021). "Tumor-infiltrating lymphocytes (TILs) were identified from hematoxylin-eosin-stained sections of paired pre- and post-NACT tumor samples from a TNBC cohort (n = 66) and expression of PD-L1, TIM-3, and LAG-3 evaluated by immunohistochemistry." (PMID 34039396, 2021). "The exhaustion of CTLs is a mechanism that occurs in the TME, suppressing the immune response of CTLs against tumor cells through the expression of inhibitory receptors such as PD-1, CTLA-4, and LAG-3." (PMID 34572263, 2021).